ENSG00000256861 (novel protein)
Gene: Protein-coding gene on chromosome 12 (122,207,779 to 122,266,423, reverse strand). Ensembl gene ENSG00000256861.
Genetic constraint (gnomAD): Missense variants: 537 observed, 682.71 expected, observed/expected ratio (o/e) 0.79, 90% interval 0.73 to 0.85. Synonymous variants: 266 observed, 268.71 expected, observed/expected ratio (o/e) 0.99, 90% interval 0.89 to 1.1.